CD34 (CD34 molecule)
Diseases named in the same sentence as CD34 in open-access papers (continued):
Sharing a sentence is not in itself a finding about the gene and the disease.
infection (continued). "CMV latency, defined by maintenance of viral genomes in the absence of new virion production, is established when infected monocytes traffic to the bone marrow and seed infection of CD34+ hematopoietic progenitor cells (HPCs)." (PMID 33668486, 2021). "During infection of CD34+ HPCs with a miR-UL148D mutant, levels of IER5 protein were significantly increased, while CDC25B showed a concordant decrease in expression." (PMID 33668486, 2021). "NS1+CD133+ and NS1+CD34+ expressions were initially low but later changed and gradually reached a maximum on D10, followed by contraction on D14 after infection." (PMID 33981874, 2021). "Both fibroblasts and hematopoietic cells express a broad proportion of the viral genome during infection, but transcripts accumulate to much greater levels in fibroblasts as compared to CD34+ HPCs." (PMID 32630219, 2020). "The optimal number of CD34+ cells can result in faster engraftment and a lower incidence of infection." (PMID 33014813, 2020). "Since EGFR signaling is regulated during lytic infection and is important for latency and reactivation in CD34+ HPCs (5, 14, –, 16, 31), we examined EGFR signaling pathway members as potential targets of HCMV miRNAs." (PMID 32759334, 2020). "The experimental design included four groups composed of male and female mice engrafted with human CD34+ hematopoietic stem cells (hCD34, HSCs), which differentiate into mature human T cells and macrophages that permit infection with HIV." (PMID 32943056, 2020). "Infection of Jurkat and CD34+ cells was performed with spinoculation, whereby the cells were centrifuged at 800 x g for 60 min at 37C° after treatment with concentrated viral media." (PMID 32039735, 2020). "Nod.Rag.Gamma (NRG) mice transplanted with human CB CD34+ cells with long-term human immune reconstitution were used to model HCMV/GLuc infection in vivo by optical imaging analyses." (PMID 32159399, 2020). "Examining the differentiation state in HSPCs following infection is far more complicated than in monocytes, as CD34+ HSPCs are a mix of pluripotent cells as well as progenitor cells in different stages of lineage commitment." (PMID 31967545, 2020). "Why then do CD34+ HPCs support latency whereas fibroblast support only replicative infection if UL133-UL138 proteins function similarly in both cells?" (PMID 32630219, 2020). "HCMV maintains latency within CD14+ monocytes and CD34+ cells of the myeloid lineage, but only after primary infection and dissemination, which is thought to occur through productive infection of oral epithelial cells." (PMID 32714883, 2020). "ULb’ genes that are largely dispensable for replication in fibroblasts have more pronounced effects on infection in CD34+ HPCs where gene expression is much lower than in fibroblasts." (PMID 32630219, 2020). "US28 suppresses MIEP activity via activation of STAT3 to prevent lytic infection and to maintain latency in CD34+ progenitor cells and CD14+ monocytes." (PMID 33096622, 2020). "EGR-1 is highly expressed during infection in CD34+ HPCs, where is serves to drive UL138 gene expression for latency." (PMID 32630219, 2020). "EGFR signaling upon infection of CD34+ cells impacts the expression of several cytokines, including IL-8 and IL-12." (PMID 33096622, 2020). "Reporter gene expression levels were quantified using flow cytometry on a BD Biosciences LSR-II at twenty-four hours post infection for 293 T and Jurkat cells, and at 72 h post infection for CD34+ HSPCs." (PMID 32039735, 2020). "UL138 is expressed in all HCMV models of infection, including fibroblasts (highly productive infection), endothelial cells (smoldering low-level productive infection), CD34+ HPCs and THP-1 cells (latent infection)." (PMID 32630219, 2020). "UL135 is expressed in all HCMV models of infection: fibroblasts, endothelial cells, CD34+ HPCs, and THP-1 cells." (PMID 32630219, 2020).
infection (continued). "Detection of HCMV viral copies by PCR showed that HCMV was detectable after infection in CD34+ HSCs and CD14+ monocytes, whereas after G-CSF treatment and reactivation the viral copies were conspicuously more abundant in CD34+ HSCs and CD169+ macrophages." (PMID 32667948, 2020). "CD34+ HSC-derived myeloid cells are semi-permissive to CMV lytic infection, with progeny being produced despite the occurrence of viral gene expression in only a small fraction of cells." (PMID 30949159, 2019). "Since herpesvirus miRNAs play key roles in latency and reactivation, HCMV miRNAs expressed at high levels during lytic infection were examined for expression in CD34+ cells." (PMID 31725809, 2019). "Our use both fibroblasts and CD34+ HPCs in these studies permits us to apply a broad array of methods to develop an in depth understanding of the biology of infection in multiple contexts." (PMID 31725811, 2019). "p24+CD34+CD7+ cell counts significantly increased from week 1 to week 3 in association with a low average CD34+CD7+ cell count at week 1 after infection and a rapid increase of CD34+CD7+ cell counts at weeks 2–3." (PMID 30761146, 2019). "Analysis of ΔmiR-US22 latently infected CD34+ HPCs for retention of viral genomic DNA at the time of reactivation indicated a significant decrease in viral genomes following ΔmiR-US22 infection in comparison to WT infected cells." (PMID 31725809, 2019). "US28 is also expressed in models of HCMV latency using CD34+ HPCs and monocytes as well as in monocyte-derived macrophages during active infection scenarios (14, 27, –, 30)." (PMID 31431555, 2019). "We previously demonstrated that CMV modulates EGFR total and cell surface levels during infection in fibroblasts (productive infection) and CD34+ HPCs (site of latency)." (PMID 31725811, 2019). "Our results clearly characterized a rapid downregulation of IFI16 during the establishment of latency in monocytes, which occurred within the first 24 h of infection and was also maintained during long-term latency in monocytes and CD34+ HPCs." (PMID 31796538, 2019). "Contrary to infection of fibroblasts that support virus replication, EGFR cell surface levels are transiently increased during infection of CD34+ cells." (PMID 31725809, 2019). "In this study, we investigated the role of signaling downstream of EGFR in productive infection in fibroblasts and in latency in CD34+ HPCs." (PMID 31725811, 2019). "Further assays and analyses revealed that CD34+CD7+CXCR4+ cells can be quickly depleted as early as 1 week after infection of the subset, and this was accompanied by the emergence of rare CD34+CD7+CD4+ cells." (PMID 30761146, 2019). "(f) Kinyoun staining of CD34+ cells after 1d and 5d of infection and quantification, as described in the methodology section, shown in the right panel." (PMID 31637998, 2019). "Confocal microscopy analysis confirmed the presence of sparse intracellular mycobacteria in purified cord blood derived CD34+ cells at 4 hr post-infection (pi)." (PMID 31637998, 2019). "Human cytomegalovirus (HCMV) infection of CD34+ hematopoietic progenitor cells (CD34+ HPCs) provides a critical reservoir of virus in stem cell transplant patients, and viral reactivation remains a significant cause of morbidity and mortality." (PMID 31431555, 2019). "Successful infection of both CD14+ and CD34+ cells has been linked to interactions between the virion and EGFR." (PMID 29547547, 2018). "US28 mRNA was first detected in latently infected THP-1 cells, and later by gene array analyses following infection of primary ex vivo cultured CD34+ HPCs, as well as naturally latently infected peripheral blood monocytes and CD34+ HPCs." (PMID 30127279, 2018). "Latent infection occurs in less differentiated CD34+ hematopoietic progenitor cells (HPCs) in the bone marrow as well as CD14+ monocytes." (PMID 30360396, 2018).
infection (continued). "A subsequent study demonstrated that infection of CD34+ cells with HCMV results in a transient activation of the pro-apoptotic protein Bak." (PMID 29547547, 2018). "A direct infection of circulating CD34+ cells by mucosal epithelial cells then a subsequent migration to and seeding of the bone marrow is possible but remains elusive." (PMID 30127257, 2018). "Significantly, more deaths related to infection occurred in the CD34+ group (16/52 vs. 19/112, p = 0.04)." (PMID 30342553, 2018). "We next optimized the donor dose to determine the multiplicity of infection (MOI) best suited for CD34 cell modification." (PMID 29565806, 2018). "When humanization of liver and immune system establishment was evident (∼5 months of age), mice were infected with HIV-1ADA 104 tissue culture infectious doses 50 (TCID50) intraperitoneally, and euthanized at 5 weeks post-infection (Hep+CD34+HIV mice)." (PMID 29361613, 2018). "In this experiment, we also stained for KSHV LANA as a marker of infection, the endothelial cell marker CD34 as well as Hematoxylin and Eosin (H&E) to visualize tissue structures." (PMID 28938025, 2017). "The HIV receptor, CD4, is usually required for infection and is expressed on CD34+ HSPCs, although at low levels compared to CD4+ T cells." (PMID 28732051, 2017). "Four days after infection, normal CD34+ cells were analyzed for GFP expression and between 35 and 50% of GFP+ cells were detected in 3 independent experiments." (PMID 29228587, 2017). "Here we show that LC and iDDC generated from pluripotent cord blood CD34+ cell precursors support productive infection with HHV-8." (PMID 28768873, 2017). "To determine how monocyte–macrophages and CD34+ progenitor cells phenotypes change during the course of infection and ART, we evaluated blood, spleen and BM cell frequencies at the study end." (PMID 28279181, 2017). "Supernatants and cells were then collected at day 2, 4, and 8 (corresponding to day 10, 12, and 16 post CD34+ cells infection), and used in titration assays or in reactivation experiments, respectively." (PMID 27683575, 2016). "Infection of the marrow-derived CD34+ cells at an MOI of 10 produced peak mean levels of 2-LTR circles in the range of 0.03–0.07 copies relative to the single copy gene." (PMID 26945863, 2016). "These resulted were indicative of a strong block in infection of marrow derived CD34+ cells, likely at the stage of nuclear entry." (PMID 26945863, 2016). "Lin- CD34+ cells decreased in numbers in bone marrow (2.84% ± 1.2) and spleen (0.05% ± 0.01) at 14 weeks post infection compared to uninfected controls (9.21% ± 0.84 and 1.5% ± 0.46), respectively." (PMID 26996968, 2016). "Infection of the marrow-derived CD34+ cells at an MOI of 10 produced peak mean copies of total viral DNA relative to the single copy gene in the range of 3–7 copies, and with no consistent change upon addition of cytokines." (PMID 26945863, 2016). "Then, neutrophils generated from CD34+ cells were evaluated with bacterial killing as well as production of reactive oxygen species (ROS), an essential neutrophil function against infection." (PMID 27737899, 2016). "NR-1ΔmiR-UL148D displayed a similar infection efficiency of Kasumi-3 cells and CD34+ HPCs and viral growth curve to NR-1." (PMID 27824944, 2016). "Animal A12309, which displayed the greatest transduction levels of CD34+ cells, also displayed the greatest level of gene marking in peripheral blood and tissue prior to infection." (PMID 26958575, 2016). "CD34+ cells from the same donors used in lytic infection assays were exposed to TB40/E virions at a calculated MOI of 10 for 4 h, prior to culture in iLC medium for 8 days." (PMID 27683575, 2016). "Infection of the marrow-derived CD34+ cells at an MOI of 1 produced peak levels of total viral DNA in the range of 0.5–1.2 copies relative to the single copy gene, with only minimal change upon incubation with cytokines." (PMID 26945863, 2016).
infection (continued). "We analysed virally encoded miRNA expression in CD34+ and CD14+ cells at 4 days post infection (dpi) with TB40 IE86-YFP." (PMID 27491954, 2016). "This indicates a strong block in infection of marrow derived CD34+ cells even at high MOIs, likely at the stage of nuclear entry." (PMID 26945863, 2016). "Infection of the mobilized CD34+ cells at MOI of 1 produced moderately high levels of total viral DNA; only very low levels of circular viral DNA containing the 2-LTR junction; and undetectable or extremely low levels of integrated proviral DNA." (PMID 26945863, 2016). "We performed similar assays for viral DNA levels formed upon infection of primary adult human peripheral mobilized CD34+ cells." (PMID 26945863, 2016). "Most CD34+ HPCs also maintained a progenitor phenotype at 10 days post-infection of NR-1 at a multiplicity of 5 PFU/cell." (PMID 27824944, 2016). "Flow cytometry analysis at day 14 post-infection showed an increase in CD34+ cells in Oct4-transfected MSCs as compared to the nontransfected clones." (PMID 25890320, 2015). "Latent infection of primary CD34+ progenitor cells by human cytomegalovirus (HCMV) results in their increased survival in the face of pro-apoptotic signals." (PMID 25957098, 2015). "Myocardial expression of NIS, VEGF and CD34 following infection with Lenti-MLC-2v-VEGF165-IRES-NIS can be detected by immunohistochemistry which is shown as brown-yellow spots." (PMID 26230833, 2015). "Previous studies reported that ×4 viral strains can infect CD34+ HSC, so that delivery of a protective gene construct (containing a C46 inhibitor that inhibits ×4 infection) to CD34+ HSC is likely to confer an additional survival advantage on G+ CD34+ HSC." (PMID 24945407, 2014). "Latent infection of CD34+ progenitors with the Merlin isolate of HCMV is known to result in an increase in secreted cIL-10." (PMID 25253336, 2014). "scAAV6 vectors containing the EGFP gene under the control of the three promoters were used to infect primary human CD34+ cells under identical conditions, and transgene expression was evaluated 72 hrs post-infection." (PMID 23516552, 2013). "HCMV initial infection is followed by the establishment of latency in CD34 (+) myeloid cells and CD14 (+) monocytes." (PMID 23717203, 2013). "At three days post infection of CD34 (+) cells only a subset of genes were expressed, whereas in CD14 (+) cells almost the entire HCMV genome showed active transcription." (PMID 23717203, 2013). "Both CD34−/− or CD43−/− mice displayed a resistant phenotype following infection with Trichuris, as measured by worm burden, immunoglobulin production and cytokine production." (PMID 23555902, 2013). "The second experimental latency system used infection of CD34 (+) cells where we isolated CD34 (+) cell populations, since evidence suggests that these cell types support HCMV latent virus." (PMID 23717203, 2013). "First, despite early conflicting studies, it became apparent that both MDDC and CD34+ precursor cell-derived DC are poorly permissive for productive HIV-1 cis infection." (PMID 24278768, 2013). "Previous studies of direct infection of CD34+ HSCs and MSCs by other persistent viruses, such as Measles virus (MV) and Cytomegalovirus (CMV) have demonstrated virus-mediated immunosuppression." (PMID 24339969, 2013). "Consistent with CD34+ hematopoietic stem cell (HSC) infection, FIX-WT and FIX-Rev infected CD14+ cells expressed UL138 transcripts through 10 dpi." (PMID 23300789, 2012). "PB CD34+ cells were harvested from H145 and transduced with the foamy vector at a multiplicity of infection of 9.9." (PMID 23028826, 2012). "Consistent with CD34+ infection, UL123 (IE1) transcript was transiently expressed during latency in infected CD14+ cells." (PMID 23300789, 2012). "Initially, we observed that the number of LSK CD34− CD135− cells increased during infection, which suggested that the LSK population contained more HSCs." (PMID 22194881, 2011).
infection (continued). "The B19 in vitro infection procedures employed here have been previously used in the documentation of functionality of mobilized, preselected (CD34+) cells." (PMID 20209110, 2010). "Using the same primer sets in umbilical cord blood CD34+ cells (infection efficiency: 14.7%, based on GFP fluorescence), we have identified an HIR (-1882 to -2971) (18/270) in a similar region as the TPA-Mat-ecoR and Jurkat-ecoR cells." (PMID 19725963, 2009). "CD34 was approximately 30% more highly expressed on day 9 post-infection in both liver and spleen of A/J in comparison with C57BL/6 mice (not shown), suggesting higher levels of haematopoiesis in A/J." (PMID 19365556, 2009). "LCs derived in vitro from CD34-expressing precursor cells, like MDDCs, mediate efficient trans-infection of T cells despite expression of langerin." (PMID 18584030, 2008). "We reported that sCD4 treatment of MDDCs and CD34-derived LCs loaded with HIV virions fully abrogated trans-infection of T cells." (PMID 18584030, 2008). "EGFP expression was observed in TN9-8GF5 amplicon-infected CD34+ cells starting at 24 h post-infection." (PMID 15673469, 2005). "Starting at 24 h after infection, CD34+ cells were examined for EGFP expression by fluorescent microscopy." (PMID 15673469, 2005). "In a separate experiment, at 36 hours post infection, the cells were stained with PE-labeled anti-CD34 and analyzed for the CD34 marker and EGFP expression." (PMID 15673469, 2005). "In our experiments we used cord blood derived CD34+ cells for infection with HCMV amplicon containing stocks or HCMV-EGFP virus." (PMID 15673469, 2005). "hESC-derived CD34+ HPCs support latency and virus reactivation, have been used to define roles for viral proteins and miRNAs in latency, and addressed heterogeneity in infection outcomes in hematopoietic subpopulations." (PMID 40736257, 2025). "The odds ratio of infection in the CD34-NSG-IL15 mice to CD34-NSG-SGM3 mice is 0.098 (p < 0.0001)." (PMID 40373766, 2025). "At Day 14 of differentiation and Day 7 post-infection of cord blood CD34+ HSPC-derived megakaryocytes, IFITM3 expression levels were lower in infected cells relative to non-infected mature megakaryocytes, as assessed by both confocal microscopy and flow cytometry." (PMID 39354676, 2025). "The CD99 signaling network demonstrated increased activity in NK cell and Platelets, with significant connection with T cell:CD4+ effector memory, T cell:CD4+ central memory and Pre‐B cell CD34‐, emphasizing their capacity to contribute to inflammatory mediators' processes after infection." (PMID 40910395, 2025). "In addition, the natural heterogeneity of the CD34+ population and the varied outcome of infection among the different subpopulations create variability between results with different donors." (PMID 40736257, 2025). "However, the outcome of the infections in mice transplanted with human CD34+ hematopoietic cells (h/NSG) drastically differs and was, to a large extent, the opposite." (PMID 41143413, 2025). "Moreover, productive infection occurs in a small subset (<1%) of CD34+ cells, specifically the CDP, CMP, and GMP subsets." (PMID 40872823, 2025). "Monocytes likely acquire virus from epithelial cells at the site of initial infection (analogous to EBV infection of epithelial cells and B cells) and traffic to the bone marrow, where they transfer infection to CD34+ HPCs, although this remains to be definitively shown." (PMID 40736257, 2025). "Interestingly, FOXO3a is a target of miR-US5-1 and miR-UL112, whose downregulation is important for inhibiting apoptosis early after infection of CD34+ HPCs." (PMID 39661658, 2024). "Interestingly, total Akt levels did not appear to be affected during WT infection of hESC-derived CD34+ HPCs, in contrast to observations during lytic infection of fibroblasts." (PMID 39661658, 2024). "Therefore, US28 is a suitable target for lytic infection, as well as for latency in monocytes and their CD34+ precursors." (PMID 39452693, 2024).